BIRC3 (baculoviral IAP repeat containing 3)
Diseases named in the same sentence as BIRC3 in open-access papers (continued):
Sharing a sentence is not in itself a finding about the gene and the disease.
cervical carcinoma (13 papers, 2006 to 2026). A carcinoma arising from either the exocervical squamous epithelium or the endocervical glandular epithelium. "In The Cancer Genome Atlas (TCGA) comprehensive characterization of cervical cancer, BIRC3 was highlighted for showing amplification events in 17% of tumors." (PMID 32595829, 2020). "BIRC3, one of the significant genes of our model, has an important role in the inhibition of apoptosis and could be related to the survival of cervical cancer cells during metastasis." (PMID 32595829, 2020). "Many of the genes, including BIRC2, BIRC3, ATF5, NUP62, FASTKD3, IDH3G, and POFUTI, have been found to be regulated by gains or losses in previous cervical cancer studies." (PMID 19911042, 2009). "While BIRC3 and CD300LG may play a role in the pathophysiology of cervical cancer metastasis, our gene expression study simply suggests a correlative connection." (PMID 32595829, 2020).
leukemia (12 papers, 2009 to 2024). A malignant (clonal) hematologic disorder, involving hematopoietic stem cells and characterized by the presence of primitive or atypical myeloid or lymphoid cells in the bone marrow and the blood. "All three 11q22.3 deletions involving ATM (sizes: 16, 17, and 18 Mb) also encompassed at least two of the other nearby leukemia-associated genes (BIRC3, ZBTB16, KMT2A, or CBL)." (PMID 36831635, 2023). "Out of 17 genes that mapped to the DISEASE database, 7 have been linked to pathogenesis of human CLL and/or other leukemias (Birc3, Wnt5a, SP140, Atr, Lyn, CD274, and Flt3), and SIFT analysis revealed that the detected mutation in Lyn is likely deleterious." (PMID 34417556, 2022). "Up-regulation of Bcl-2 and other anti-apoptotic genes (Bcl-xl, Bcl-2L10, Bag3 and Iap2/Birc3) have been also documented in Bu-resistant leukemia cell lines, which are capable of evading busulfan mediated G2-arrest and apoptosis." (PMID 38321093, 2024). "Some of these AM genes are known to be dysregulated in leukaemia: up regulation of BIRC3 and down regulation of APAF1, CIDEB, FAS, TNFRSF25, TNFSF10 were previously identified by our group as specific alterations of AM genes in leukemic cells." (PMID 20642818, 2010). "Down regulation of PI3K/AKT signaling using the IAP inhibitor, GDC-0152, which targets BIRC2, BIRC3, and XIAP has been shown to result in the induction of apoptosis in human leukemia cells." (PMID 27074575, 2017).
viral infection (11 papers, 2012 to 2025). "Since BIRC genes may play roles in cell fate following viral infection, we tested whether the viral infection-associated cytokine, IFNG, could enhance BIRC2 and/or BIRC3 expression." (PMID 37289679, 2023). "The 7th key gene BIRC3 drives the host response against viral infections." (PMID 35390032, 2022). "Since BIRC2/BIRC3 and TRAF2/3 could form a cytoplasmic complex, where BIRC2/BIRC3 mediated ubiquitination and degradation of TRAF3, the roles of BIRC2/BIRC3 in viral infection were extensively investigated." (PMID 34887869, 2021). "In the disease association analysis (neoplasms, cancer or viral infections, breast neoplasms, neuroblastoma), the LMO3, MYB and BIRC3 oncogenes were also significantly upregulated whereas the WISP2, IGFBP5 and RASSF2 tumour suppressor genes were significantly downregulated in FFs compared to NFs." (PMID 28717200, 2017). "The BIRC2 and BIRC3 genes (which had altered expressions in ASD, asthma, ear infection, and bacterial and viral infections) are members of the inhibitor-of-apoptosis protein family and are key regulators of NOD1 and NOD2 innate immunity signaling." (PMID 27842596, 2016). "A link between the gene expression of BIRC3 and MX1 has been hypothesized as part of a small group of genes controlling the host response against viral infections, including human herpes virus type 6Α (HHV-6Α) infection." (PMID 33301474, 2020). "Other genes, including Gpr84 and Birc3, as well as expressed transcripts AW112010 and BC023105 were consistently upregulated in activated microglia and astrocytes and were also upregulated in the CNS following virus infection." (PMID 26214311, 2015). "In addition, other genes including Birc3 and Gpr84 as well as two expressed sequences AW112010 and BC023105 were found to be induced in both microglia and astrocytes and were upregulated in the CNS following virus infection." (PMID 26214311, 2015). "Conversely, and despite potential roles for these two BIRCs in cell fate determination during viral infections, the antiviral cytokine, IFNG, did not acutely induce expression of either BIRC2 or BIRC3." (PMID 37289679, 2023).
bladder cancer (10 papers, 2013 to 2023). "Mechanistically, WDR5 regulated various functions in bladder cancer by mediating the transcription of cyclin B1, cyclin E1, cyclin E2, UHMK1, MCL1, BIRC3 and Nanog by histone H3 lysine 4 trimethylation." (PMID 25656485, 2015). "In sum, these findings indicate that WDR5 enhances bladder cancer cell anti-apoptosis and chemoresistance to cisplatin by regulating MCL1 and BIRC3, and it may be a potential target for drug development." (PMID 25656485, 2015).
hepatocellular carcinoma (9 papers, 2012 to 2025). A malignant tumor that arises from hepatocytes. "Studies have shown that BIRC3 mRNA is upregulated in hepatocellular carcinoma (HCC) tissues, and the high expression of cIAP2 encoded by BIRC3 promotes HCC proliferation and migration." (PMID 39301019, 2024). "Studies have shown that the knockdown of BIRC3 gene expression significantly reduces the activity of the Nf-Kappa B pathway in hepatocellular carcinoma (HCC)." (PMID 40243536, 2025). "For example, in hepatocellular carcinoma (HCC) BIRC3 could promote HCC epithelial-mesenchymal transition (EMT), cell migration and metastasis by upregulating MAP3K7 to induce ERK1/2 phosphorylation." (PMID 38130918, 2023). "Additionally, the lower expression of BIRC3 in HK4-treated cells might also play a protective role in our cell model, since inhibition of BIRC3 reduced hepatocellular carcinoma and progression of metastases." (PMID 36860523, 2023).
influenza infection (9 papers, 2016 to 2023). "Transcription of BIRC3, which inhibits apoptotic responses to inflammation in influenza infection, is also cooperatively regulated by GR and NF-κB." (PMID 33891947, 2021). "For example, mice with the BIRC3 deficiency exhibited the increased susceptibility and mortality to influenza A virus infection, and BIRC3-dependent antagonism of RIP3-mediated programmed necrosis protected the mice from influenza infection by maintaining pulmonary tissue homeostasis." (PMID 34887869, 2021).
lymphoma (9 papers, 2010 to 2024). A malignant (clonal) proliferation of B- lymphocytes or T- lymphocytes which involves the lymph nodes, bone marrow and/or extranodal sites. "This is in fact proposed as a therapeutic target in BIRC3‐mutated lymphomas and is currently under investigation." (PMID 33413657, 2021). "BIRC3 mutations appear in up to 4% of newly diagnosed CLL, and rarely in other low-grade lymphomas such as MZL and WM." (PMID 37951851, 2024). "The role of BIRC3 warrants a more profound analysis in SMZL to clarify its role in these specific lymphomas." (PMID 34590593, 2021). "Other lymphomas, including MCL, rely on NF-kB activation and BIRC3 disruption play a role in their pathogenesis." (PMID 33413657, 2021).
mantle cell lymphoma (8 papers, 2015 to 2024). Mantle cell lymphoma is a rare form of malignant non-Hodgkin lymphoma affecting B lymphocytes in the lymph nodes in a region called the ``mantle zone''. "A focus on mature B-cell neoplasms reveals how BIRC3 mutations are common to another lymphoid malignancy: mantle-cell lymphoma (MCL)." (PMID 33413657, 2021). "Because mutations in other NF-κB pathway genes, including BIRC3, TRAF2, TRAF3, MAP3K14 and CARD11, have been associated with ibrutinib resistance in mantle cell lymphoma, we next investigated whether mutations in NFKBIE could also affect the response to ibrutinib treatment." (PMID 38486128, 2024). "BIRC3 is mutated in mantle cell lymphoma and GCB DLBCL but not in Burkitt's lymphoma or ABC DLBCL." (PMID 26377837, 2015). "In mantle cell lymphoma (MCL), resistance to ibrutinib (the BCR antagonist that targets Bruton’s tyrosine kinase) is characterised by aberrant non-canonical NF-kB signalling due to mutations in TRAF2 and BIRC3." (PMID 37835430, 2023). "Mutations in key genes of the alternative NF-kB pathway, such as BIRC3, confer resistance to BTK inhibitors in mantle cell lymphoma (MCL), that can be overcome with the addition of NIK inhibitors." (PMID 34202439, 2021).
oral squamous cell carcinoma (7 papers, 2011 to 2024). "Down-regulation of BIRC3 can enhance the drug sensitivity of 5-FU in oral squamous cell carcinoma, esophageal adenocarcinoma and other malignant tumors in later studies." (PMID 38762737, 2024). "The high expression of BIRC3 in oral squamous cell carcinoma (OSCC) was significantly correlated with lymph node metastasis, decreased survival rate, and increased cancer recurrence rate." (PMID 38130918, 2023). "Similarly, in oral squamous cell carcinoma, circDOCK1 was identified to suppress cell apoptosis via inhibition of miR-196a-5p by targeting BIRC3." (PMID 34876132, 2021).
asthma (6 papers, 2013 to 2023). "Baculoviral IAP repeat-containing 3 (BIRC3) which encodes a member of the IAP family of proteins upregulated in the asthma expression profile dataset." (PMID 35287655, 2022). "In the ROC analysis of the GSE76262 dataset, the area under the curve (AUC) of ROC was 0.7906 (p < 0.0001), meaning that BIRC3 expression has a good diagnostic capacity in asthma." (PMID 35287655, 2022). "Consistently, BIRC3 protein in induced sputum supernatant remarkably increased in asthma (p = 0.0001), and the AUC of the ROC curve was 0.8906 (p < 0.0001), which further demonstrate a good diagnostic capacity of BIRC3 in asthma." (PMID 35287655, 2022). "It was reported that BIRC3 was upregulated in asthma and was predicted as a pathogenic gene involved in childhood asthma." (PMID 35287655, 2022). "BIRC3 exhibits a noninvasive diagnostic value and targeted inhibition of BIRC3 might be a potential asthma therapy." (PMID 35287655, 2022). "Nemours studies found that BIRC3 protein inhibits apoptosis, which could impact susceptibility to asthma." (PMID 35287655, 2022). "Similarly, we found that BIRC3 mRNA and protein were significantly upregulated in asthma, and the results of AUC demonstrated its good diagnostic capacity." (PMID 35287655, 2022). "Upregulated BIRC3 may act as a pathogenic gene involved in asthma through Th2 cytokines activation." (PMID 35287655, 2022). "Studies have indicated that BIRC3 regulates immune-related lung diseases, including asthma and Klebsiella pneumoniae pneumonia." (PMID 38274787, 2023). "Our data raise the possibility that intraepithelial MCs and the release of tryptase are involved in the increased epithelial expression of BIRC3 present in the asthma cohort." (PMID 37408273, 2023). "In the present study, we identified BIRC3, a sputum biomarker, and explored its potential role in asthma using bioinformatical analysis." (PMID 35287655, 2022). "BIRC3 significantly increased in induced sputum of asthma and positively correlated with airway eosinophilic and peripheral blood allergic inflammation, type 2 cytokines, and airway obstruction." (PMID 35287655, 2022). "In conclusion, we identified BIRC3 mRNA and protein significantly increased in induced sputum of asthma and were positively correlated with Type 2 airway inflammation." (PMID 35287655, 2022). "Consistently, we detected IL-4, IL-5, IL-13, IL-25, IL-10, IL-33, and TSLP in induced sputum of asthma and proved a positive correlation between BIRC3 and these cytokines." (PMID 35287655, 2022). "To search the underlying mechanism regulated by BIRC3 in asthma, we conducted KEGG pathway enrichment using 13 overlapped genes and found that BIRC3 is mainly enriched in cell apoptosis and necrosis." (PMID 35287655, 2022). "Increased BIRC3 expression may contribute to asthma pathogenesis by influencing eosinophilic and allergic inflammation." (PMID 38274787, 2023). "As signaling from many PRRs converges on NF-κB, it is perhaps not surprising that polymorphisms in BIRC3 have been associated with asthma." (PMID 37289679, 2023). "Increased BIRC3 might be involved in the pathogenesis of asthma by affecting the eosinophilic and allergic inflammation." (PMID 35287655, 2022). "Finally, we selected the most significant differentially expressed gene BIRC3 (p = 2.85E−06) as the signature gene for further validation, which was significantly upregulated in asthma (p < 0.0001)." (PMID 35287655, 2022). "However, more experiments’ verifications are needed to explore the exact molecular mechanism of BIRC3 in asthma." (PMID 35287655, 2022). "However, there are few reports about the mechanism of BIRC3 involved in asthma, subsequent experiments' validations are needed." (PMID 35287655, 2022). "In addition, BIRC3 expression correlates with markers of severe asthma, suggesting BIRC3 could contribute to a more prolonged, or more severe, inflammation." (PMID 37289679, 2023).
asthma (continued). "However, there was few research on studying the clinical implication of BIRC3 in asthma." (PMID 35287655, 2022). "Therefore, we speculated that upregulated BIRC3 potentially affects Th2 immune inflammation to participate in airway eosinophilic and allergic inflammation of asthma." (PMID 35287655, 2022). "In this study, we aimed to identify upregulated BIRC3 that may act as a sputum biomarker in asthma based on the microarray dataset of GSE76262, validate BIRC3 expression using qRT-PCR and ELISA in clinical patients’ samples, and explore the clinical implication of BIRC3 in induced sputum of asthma." (PMID 35287655, 2022). "Finally, we found that increased BIRC3 was positively correlated with airway eosinophilic inflammation, Th2 cytokines secretion, and airway obstruction, indicating that upregulated BIRC3 may participate in the pathogenesis of asthma." (PMID 35287655, 2022). "While they show strong links, the mechanistic understanding of increased BIRC3 in sputum from patients with asthma is not known." (PMID 37408273, 2023). "BIRC3 was screened as a candidate gene in the GSE76262, which was highly expressed in asthma." (PMID 35287655, 2022). "Besides, we found a positive correlation between BIRC3 and IL-10, IL-33, and TSLP in induced sputum of asthma (p < 0.05)." (PMID 35287655, 2022). "Interestingly, the expression of BIRC3 in GSE76262 was significantly positively correlated with inflammatory cytokines IL-4, IL-5, IL-13, and IL-25 expression (p < 0.05), which implied that BIRC3 may play an important role in the pathogenesis of inflammation in asthma." (PMID 35287655, 2022).
liver cancer (6 papers, 2021 to 2026). An epithelial or non-epithelial malignant neoplasm that arises from the liver. "Apoptosis genes, such as BIRC3, promote EMT in liver cancer." (PMID 36980175, 2023).
Sepsis (6 papers, 2007 to 2025). Sepsis is defined as life-threatening organ dysfunction caused by a dysregulated host response to infection. "With regard to apoptosis, both pro-apoptotic (COP1, GADD45B and RIPK2) and anti-apoptotic (TNFAIP3 and BIRC3) genes were induced in the early stages of sepsis." (PMID 17324256, 2007). "In keeping with a role for regulators of apoptosis in the pathogenesis of sepsis, members of the IAP family, including NAIP/BIRC1 and BIRC3, are downregulated in immune cells in patients with sepsis, as is the BIRC6 ubiquitination target SMAC." (PMID 35866869, 2022).
splenic marginal zone lymphoma (6 papers, 2016 to 2023). Splenic marginal zone lymphoma is a rare, indolent B-cell non-Hodgkin lymphoma characterized by abnormal clonal proliferation of mature B-lymphocytes with involvement in the spleen, bone marrow and, frequently, the blood. "It was reported that somatic mutations of BIRC3 (cIAP2) were detected in 11% of splenic marginal zone lymphoma." (PMID 36119107, 2022). "BIRC3 mutations have been identified in various small B cell lymphomas including chronic lymphocytic leukemia (CLL) and splenic marginal zone lymphoma (SMZL)." (PMID 27993143, 2016). "Meanwhile, BIRC3 mutations are specifically found in CLL and marginal zone lymphoma of the spleen." (PMID 33325634, 2021).
triple-negative breast carcinoma (6 papers, 2017 to 2022). An invasive breast carcinoma which is negative for expression of estrogen receptor (ER), progesterone receptor (PR), and human epidermal growth factor receptor 2 (HER2). "In triple negative breast cancer, HCP5 as a ceRNA to regulate BIRC3 by sponging miR-219a-5p, thereby promoting cancer progression." (PMID 34923990, 2021).
esophageal adenocarcinoma (5 papers, 2020 to 2025). A malignant tumor with glandular differentiation arising predominantly from Barrett mucosa in the lower third of the esophagus. "Research focused on Barrett’s esophagus and esophageal adenocarcinoma have also suggested that BIRC2, BIRC3, MMP12, MYC, PVT1, and YAP1 may be ecDNA-related oncogenes." (PMID 40569942, 2025).
gastric cancer (5 papers, 2019 to 2024). A primary or metastatic malignant neoplasm involving the stomach. "In addition to the gastric cancer epithelial cells, we found that H. pylori also activated the expression of BIRC3 eRNA and mRNA and suppressed Raptinal-induced caspase-3 activation in human gastric organoids." (PMID 32820150, 2020). "Genes, such as SERPINA3, BIRC3, and CREBRF, are liable for the proliferation of various cancer cells, such as endometrial cancer and gastric cancer, but these genes may be linked with the proliferation of BRCA cells." (PMID 31311202, 2019). "We examined the available chromatin immunoprecipitation-sequencing (ChIP-seq) datasets for histone marks in various gastric cancer cell lines, and found that H3K27Ac was enriched around the −10 kb region, upstream of TSS and the promoter region of BIRC3." (PMID 32820150, 2020).
lung adenocarcinoma (5 papers, 2005 to 2025). A carcinoma that arises from the lung and is characterized by the presence of malignant glandular epithelial cells. "In contrast to lung adenocarcinoma, survival analysis of the TCGA lung squamous cell carcinoma (LUSC) dataset revealed that the expression levels of BIRC3, CXCL5, DKK1, FOSL1, and MYC exhibited limited association with patient survival." (PMID 39858622, 2025). "While increased staining for cIAP-2/BIRC3 in human lung adenocarcinomas has been reported, levels of cIAP-2/BIRC3 in IEN lesions in lung epithelium have not been reported." (PMID 16332260, 2005). "Interestingly, we also found that BIRC3 mRNA expression was accumulated conspicuously in lung adenocarcinoma tissues but weakened in lung squamous cell carcinoma tissues in the TCGA dataset." (PMID 34692492, 2021). "Additional studies are needed to explore if BIRC3 may serve as a potential biomarker of lung adenocarcinoma." (PMID 34692492, 2021). "cIAP-2/BIRC3 is expressed in lung adenocarcinoma cell lines and can be induced by TNF-α." (PMID 16332260, 2005). "The expression levels of AREG, BIRC3, DKK1, EREG, FOSL1, MYC, and PLAU are negatively correlated with the survival ratio, and are significantly higher in the TSPX-low lung adenocarcinoma samples, compared to TSPX-high lung adenocarcinoma samples." (PMID 39858622, 2025). "Our results showed that AKT2, BIRC3, and ERK are potential targets of HSDL2 in lung adenocarcinoma." (PMID 32211805, 2020). "Taken together, our results suggest that TSPX may suppress the development and/or progression of lung adenocarcinoma by downregulating AREG, BIRC3, DKK1, EREG, FOSL1, MYC, and PLAU, which could exacerbate lung adenocarcinoma, and upregulating the tumor suppressor CACNA2D2." (PMID 39858622, 2025).